CLTCL1 (clathrin heavy chain like 1)
Description:
Clathrin is the major protein of the polyhedral coat of coated pits and vesicles. Two different adapter protein complexes link the clathrin lattice either to the plasma membrane or to the trans-Golgi network (By similarity).
Synonyms: CLH22; CLTCL; CLTD; CHC22
Tractability: Antibody: its Gene Ontology location is reachable by antibodies, with high confidence; UniProt places it where antibodies can reach, with medium confidence. PROTAC: ubiquitination databases record sites on it; its protein half-life has been measured.
Gene: Protein-coding gene on chromosome 22 (19,179,320 to 19,291,774, reverse strand). Ensembl gene ENSG00000070371.
Subcellular location: Cytoplasmic vesicle membrane; Membrane, coated pit
Subcellular location (Human Protein Atlas): Vesicles
Pathways (Reactome):
Vesicle-mediated transport: Cargo recognition for clathrin-mediated endocytosis; Clathrin-mediated endocytosis; Formation of annular gap junctions; Gap junction degradation
Developmental Biology: EPH-ephrin mediated repulsion of cells
Gene Ontology:
Molecular function: protein binding; clathrin light chain binding; structural molecule activity
Biological process: mitotic cell cycle; positive regulation of D-glucose import; receptor-mediated endocytosis; retrograde transport, endosome to Golgi; anatomical structure morphogenesis; intracellular protein transport; vesicle-mediated transport
Cellular component: clathrin-coated pit; clathrin-coated vesicle; coated vesicle; early endosome; extracellular exosome; late endosome; membrane; plasma membrane; recycling endosome; sorting endosome; spindle; trans-Golgi network; clathrin complex; clathrin-coated endocytic vesicle; cytosol; clathrin coat of trans-Golgi network vesicle; cytoplasmic vesicle membrane
Genetic constraint (gnomAD): Loss-of-function variants: 156 observed, 179.44 expected, observed/expected ratio (o/e) 0.87, 90% interval 0.76 to 0.99. The upper end of that interval is the gene's LOEUF score, 0.99, which puts it in group 4 of 6, group 1 being the genes least tolerant of losing a copy. Missense variants: 1,859 observed, 2,039.8 expected, observed/expected ratio (o/e) 0.91, 90% interval 0.88 to 0.95. Synonymous variants: 748 observed, 772.22 expected, observed/expected ratio (o/e) 0.97, 90% interval 0.91 to 1.03.
Cancer hallmarks: invasion and metastasis (suppresses)
Homologues: Orthologues: macaque CLTCL1 (97% identical), dog CLTCL1 (92% identical), guinea pig CLTCL1 (91% identical), rabbit CLTCL1 (89% identical), tropical clawed frog cltcl1 (88% identical), chimpanzee CLTCL1 (86% identical), zebrafish cltcl1 (78% identical), Drosophila melanogaster Chc (77% identical), Caenorhabditis elegans chc-1 (69% identical). Paralogues in human: CLTC (85% identical), CLHC1 (7% identical).
Diseases named in the same sentence as CLTCL1 in open-access papers:
CLTCL1 is named in the same sentence as 26 diseases in open-access papers, as found by Europe PMC text mining. Sharing a sentence is not in itself a finding about the gene and the disease. The quoted sentences say what the papers report.
DiGeorge syndrome (5 papers, 2019 to 2023). "CLTCL1 encodes a major protein of the polyhedral coat of coated pits and vesicles, which is associated with multiple syndromes, including DiGeorge syndrome and Velo-Cardio-Facial syndrome." (PMID 37107637, 2023). "The patient affected by DiGeorge syndrome showed a 2 Mb pathogenic deletion on chromosome 22 from CLTCL‐1 gene to LRZTR1 gene." (PMID 33838017, 2021). "Interestingly, the single gene, CLTCL1, found to be similarly hypomethylated in both the 16p11.2del and CHD8+/− signatures, is found in the 22q11.2 deletion syndrome (22qDS; OMIM# 611867) deletion region." (PMID 31311581, 2019).
Insulin resistance (3 papers, 2017 to 2024). Increased resistance towards insulin, that is, diminished effectiveness of insulin in reducing blood glucose levels. "While we would not expect the major CLTCL1 polymorphism to directly influence the development of T2D, CHC22 accumulates on the expanded GSC that forms in cases of insulin-resistant T2D, so its variation could potentially exacerbate insulin resistance to different degrees." (PMID 31159924, 2019).
breast carcinoma (2 papers, 2013 to 2021). "Decreased CLTCL1, clathrin, has been identified as an early change in breast carcinomas and as a driver in oral squamous cell carcinoma." (PMID 33556121, 2021). "CLTCL1 encodes the heavy chain of clathrin, and the expression and/or activity of clathrin has been found to be associated with bladder cancer, TRAIL-resistant breast cancer, and uptake of some chemotherapeutic agents." (PMID 23467907, 2013).
osteosarcoma (2 papers, 2021 to 2024). A usually aggressive malignant bone-forming mesenchymal neoplasm, predominantly affecting adolescents and young adults. "In adjacent normal tissues, the protein expression levels of CLTCL1 were significantly higher than those observed in osteosarcoma samples." (PMID 39015570, 2024). "Specifically, the mRNA and protein expression levels of CLTCL1 were significantly reduced in osteosarcoma cells, indicating its potential role as a tumor suppressor gene." (PMID 39015570, 2024). "Inhibition of CLTCL1 expression led to increased proliferation and migration of osteosarcoma cells, along with a significant reduction in apoptosis, validating its role as a protective molecular marker." (PMID 39015570, 2024). "In comparison to osteosarcoma samples, the mRNA expression levels of the CLTCL1, MTM1, and MLH1 genes were significantly elevated in adjacent normal tissues (P=0.015, P=0.009, and P<0.001, respectively)." (PMID 39015570, 2024). "Compared to the control group, a significant decrease in the apoptosis rate of osteosarcoma cells was observed following CLTCL1 gene knockdown (P<0.001), while a substantial increase was noted after SQLE gene knockdown (P<0.001) and EDIL3 gene knockdown (P<0.01)." (PMID 39015570, 2024). "Furthermore, the CLTCL1 gene expression was significantly greater in MSCs than in the osteosarcoma cell lines." (PMID 39015570, 2024). "Bioinformatics analysis suggested that CLTCL1 might exert protective effects in osteosarcoma." (PMID 39015570, 2024). "Knockdown of three of these genes—CLTCL1, EDIL3, and SQLE—resulted in substantial changes in proliferation rate, migration capacity, and apoptosis rate of osteosarcoma cells." (PMID 39015570, 2024). "Additionally, when compared to MSC cell lines, human osteosarcoma cell lines showed significantly higher protein expression levels of SQLE and EDIL3, whereas CLTCL1 demonstrated significantly higher protein expression levels in MSC cell lines than in human osteosarcoma cell lines." (PMID 39015570, 2024). "According to all experimental results, CLTCL1, MTM1, and MLH1 are likely tumor suppressor genes exerting inhibitory effects on osteosarcoma development, while SQLE and EDIL3 may function as targets promoting tumor proliferation, thus presenting new therapeutic potential." (PMID 39015570, 2024). "We found that down‐regulation of CLTCL1 did not impair cell growth in osteosarcoma." (PMID 34185412, 2021).
autism (1 paper, 2019). Persistent deficits in social interaction and communication and interaction as well as a markedly restricted repertoire of activity and interest as well as repetitive patterns of behavior. "The homozygous R125C mutation in CLTCL1, inherited from heterozygous parents, was predicted to be damaging and has been identified in patients with autism." (PMID 31354784, 2019).
bipolar disorder (1 paper, 2023). A disorder of the brain that causes unusual shifts in mood, energy, activity levels and the ability to carry out day-to-day tasks. "However, we can identify five top genes at 22q11.2 associated with BMI (YDJC, CCDC116, PPIL2, THAP7, UBE2L3), primarily located outside the canonical CNV region (LCR D-E), three with bipolar disorder (TMEM191B, TUBA8, PPIL2), six with ASD (CLTCL1, AC004471." (PMID 37267418, 2023).
cervical adenocarcinoma (1 paper, 2026). An adenocarcinoma arising from the cervical epithelium. "When comparing the 54 primary and 36 metastatic cervical adenocarcinoma samples in our study, BCL6 and CLTCL1 mutations were found exclusively in metastatic tumors." (PMID 41597409, 2026).
diabetes (1 paper, 2016). "Foremost, all four patients were affected by a homozygous, compound heterozygous mutations or de novo variant in a diabetes-relevant (CLTCL1 and PDZD2) or pancreatic expressed (MORN1 and ZNF330) gene." (PMID 28007035, 2016).
metastatic tumors (1 paper, 2026). "BCL6 was present in 11.1% of metastatic tumors (n = 4), while CLTCL1 alterations appeared in one metastatic sample (2.8%)." (PMID 41597409, 2026).
psychosis (1 paper, 2019). "The corresponding 22q11.2-haplotype analysis revealed an association between a specific “risk” haplotype, contained two “damaging” variants in PRODH and CLTCL1 genes, and psychosis." (PMID 30710087, 2019).
Salmonella Infections (1 paper, 2019). Infections with bacteria of the genus SALMONELLA. "Clonal mutants of CLTCL1 showed strong resistance to Salmonella infection, with residual Salmonella GFP-positive cells being at only 18.5% ± 5.5% for the CLTCL1_B10_F10 compound heterozygous mutant clone compared to the WT." (PMID 31594818, 2019).
schizophrenia (1 paper, 2019). A major psychotic disorder characterized by abnormalities in the perception or expression of reality. "A mutation in CLTCL1 located on chromosome 22q11.2 has also been associated with susceptibility to schizophrenia." (PMID 31354784, 2019).
cancer (9 papers, 2013 to 2022). A tumor composed of atypical neoplastic, often pleomorphic cells that invade other tissues. "Indeed, candidate genes involved in maintaining genome stability, such as RAE1, SETD2, and CLTCL1, are attractive candidates for broad cancer susceptibility." (PMID 34067022, 2021). "This is in line with our observation of an increased personal history of cancer, including cancer beyond CMM and RCC, in cases with CLTCL1 or SETD2 mutations." (PMID 34067022, 2021). "Six pDGVs in the PINX1, MOB1A, CLTCL1, PRR5, CCDC136, and TRIM32 genes involved the exact amino acid residues affected by known somatic cancer variants." (PMID 33273457, 2020). "Among Cancer Gene Census genes, 1346 events were detected in 947 different loci, with the most recurrent ones being those in CLTCL1 (24 cases), CSMD3 (21 cases), MYH9 (20 cases), ANK1 (19 cases), TPR (19 cases), MYH11 (18 cases), PTPN13 (18 cases), and POLQ (17 cases)." (PMID 33809641, 2021). "Specific missense mutation matches have been found to six proteins from the COSMIC Cancer Gene Census database (FLNA, RPL22, SDHA, NFATC2, NPM1, and CLTCL1)." (PMID 31316139, 2019). "To date, several more ALK hybrid proteins have been identified in various cancer types, such as TRK-fused gene (TFG)-ALK, tropomyosin 3 (TPM3)-ALK, tropomyosin 4 (TPM4)-ALK, clathrin heavy chain-like 1 (CLTCL1)-ALK, and moesin (MSN)-ALK." (PMID 23667670, 2013).
tumor (7 papers, 2017 to 2025). "The persistence of clonal mutations in ATM, PTK2, GLI3 and CLTCL1 in all tumour locations analysed in samples from diagnosis and at relapse in patient CB1002 could indicate the relevance of these SNVs for tumour progression." (PMID 34815394, 2021). "Notably, the expression trends of KIAA0319, DERL1, SGK3, and CLTCL1 in tumor tissues mirrored those observed in the cell lines, providing consistency between in vitro and in vivo observations." (PMID 39792732, 2025). "To test whether these tumor‐suppressive effects were not attributed to the loss of clathrin function, we knocked down the expression of CLTCL1, which is another isoform of clathrin heavy chain." (PMID 34185412, 2021). "However, in the GSE6631 dataset, CLTCL1 expression was not significantly different between normal and tumor groups." (PMID 37588994, 2023).
CLTCL1 also shares sentences with these, for which no sentence is quoted: infection (2 papers); bladder cancer (1); colorectal cancer (1); congenital heart disease (1); Huntington disease (1); Hyperglycemia (1); leukemia (1); meningioma (1); myopathies (1); oral squamous cell carcinoma (1); seizure disorder (1); type 2 diabetes (1).